TXNDC5 (thioredoxin domain containing 5)
Description:
Protein disulfide isomerase of the endoplasmic reticulum lumen involved in the formation of disulfide bonds in proteins. Can reduce insulin disulfide bonds.
Synonyms: ERp46; MGC3178; FLJ21353; FLJ90810; EndoPDI; Hcc-2; PDIA15; HCC2; STRF8; UNQ364
Tractability: Antibody: its Gene Ontology location is reachable by antibodies, with high confidence; UniProt predicts a signal peptide or a membrane-spanning region. PROTAC: ubiquitination databases record sites on it; its protein half-life has been measured.
Gene: Protein-coding gene on chromosome 6 (7,881,440 to 7,911,011, reverse strand). Ensembl gene ENSG00000239264.
Subcellular location: Endoplasmic reticulum lumen
Subcellular location (Human Protein Atlas): Endoplasmic reticulum
Pathways (Reactome):
Vesicle-mediated transport: Golgi Associated Vesicle Biogenesis; Lysosome Vesicle Biogenesis
Immune System: Neutrophil degranulation
Gene Ontology:
Molecular function: protein binding; protein disulfide isomerase activity; protein-disulfide reductase activity
Biological process: negative regulation of apoptotic process; protein folding
Cellular component: extracellular exosome; azurophil granule lumen; endoplasmic reticulum; endoplasmic reticulum lumen; extracellular region; lysosomal lumen; cytoplasm; endomembrane system; intracellular organelle lumen
Genetic constraint (gnomAD): Loss-of-function variants: 46 observed, 55.08 expected, observed/expected ratio (o/e) 0.84, 90% interval 0.66 to 1.07. The upper end of that interval is the gene's LOEUF score, 1.07, which puts it in group 4 of 6, group 1 being the genes least tolerant of losing a copy. Missense variants: 599 observed, 530.88 expected, observed/expected ratio (o/e) 1.13, 90% interval 1.05 to 1.21. Synonymous variants: 241 observed, 220.63 expected, observed/expected ratio (o/e) 1.09, 90% interval 0.98 to 1.22.
Homologues: Orthologues: chimpanzee TXNDC5 (99% identical), macaque BLOC1S5 (96% identical), pig TXNDC5 (84% identical), mouse Txndc5 (82% identical), rat Txndc5 (82% identical), dog TXNDC5 (74% identical), guinea pig TXNDC5 (73% identical), rabbit TXNDC5 (70% identical), zebrafish txndc5 (57% identical), tropical clawed frog txndc5 (55% identical), Drosophila melanogaster prtp (40% identical), Caenorhabditis elegans pdi-1 (23% identical), and 1 more. Paralogues in human: P4HB (26% identical), PDIA2 (25% identical), PDIA3 (24% identical), PDIA4 (24% identical), PDIA5 (21% identical), PDILT (19% identical), PDIA6 (18% identical), ERP44 (18% identical), TMX3 (17% identical), TXNDC11 (16% identical), TMX4 (9% identical), TMX1 (8% identical), and 1 more.
Diseases named in the same sentence as TXNDC5 in open-access papers:
TXNDC5 is named in the same sentence as 103 diseases in open-access papers, as found by Europe PMC text mining. Sharing a sentence is not in itself a finding about the gene and the disease. The quoted sentences say what the papers report.
hepatocellular carcinoma (12 papers, 2014 to 2024). A malignant tumor that arises from hepatocytes. "In cancer, the SNPs in TXNDC5 gene are significantly associated with genetic susceptibility to a variety of cancers, including cervical cancer, hepatocellular carcinoma, liver cancer and esophageal cancer." (PMID 38629066, 2024). "Thioredoxin domain containing 5 (TXNDC5) is also implicated in the regulation of cancer progression of hepatocellular carcinoma, prostate cancer, and colorectal cancer." (PMID 37303736, 2023). "TXNDC5 modulated adiponectin signalling by interacting with adiponectin receptor 1 (AdipoR1) and contributed to increased risk of hepatocellular carcinoma development." (PMID 29792171, 2018). "In Zang’s study, Circ-0000517 accelerated hepatocellular carcinoma progression through upregulation of TXNDC5 by sponging miR-1296-5p." (PMID 36556238, 2022). "TXNDC5 is involved in protein folding and chaperone activity and is abnormally expressed in many cancers, such as non-small cell lung cancer, prostate cancer, gastric adenocarcinoma, colon cancer, and hepatocellular carcinoma." (PMID 37686174, 2023). "CircRNA_0078710 and circRNA_0000517 promote the development of hepatocellular carcinoma (HCC) by upregulating TXNDC5 via miRNA-431-5p and miRNA-1296-5p, respectively." (PMID 38666927, 2024). "SNP analysis of the TXNDC5 gene found that two SNPs (rs1225944 and rs1225943) of TXNDC5 are related to the development of hepatocellular carcinoma (HCC)." (PMID 35934705, 2022). "As a critical member of the protein disulfide isomerase (PDI) family, the aberrant overexpression of TXNDC5 protein has been investigated in multiple human tumors, including esophageal squamous cell carcinoma, cervical cancer, lung cancer, and hepatocellular carcinoma." (PMID 35117988, 2021). "As the knockdown efficiency of TXNDC5 was low in HEK293T cells and plasmids and transfection efficiency was extremely low in siRNA-transfected hepatoma cells, we selected A549 cells for the next study." (PMID 38548704, 2024). "Among them, thioredoxin domain-containing protein 5 (TXNDC5) is reportedly involved in several malignancies, including cervical cancer, prostate cancer, and hepatocellular carcinoma." (PMID 31331361, 2019). "Regarding hepatocellular carcinoma tissue, TXNDC5 expression is increased in poorly differentiated hepatocellular carcinomas but not in highly differentiated tumors." (PMID 38629066, 2024).
gastric cancer (11 papers, 2014 to 2025). A primary or metastatic malignant neoplasm involving the stomach. "Upregulating the expression of TXNDC5 in gastric cancer cells can significantly increase the percentage of cells in the G2/M phase, whereas downregulating can increase the percentage of cells in the 0/G1 phase." (PMID 35934705, 2022). "The silencing of TXNDC5 expression also restrains the growth and proliferation of gastric cancer cells." (PMID 29207620, 2017). "A study has found that there is an interaction between PRDX4 and TXNDC5 protein molecules in gastric cancer, and PRDX4 may reduce lymphocyte infiltration, affect the expression of multiple immune checkpoints, leading to anti-tumor immune suppression." (PMID 41445793, 2025). "Gastric cancer is a prevalent malignant tumor globally in which TXNDC5 overexpression contributes to cell invasion and metastasis and may correlate with poor tumor differentiation and prognosis." (PMID 38666927, 2024). "According to these studies, the TXNDC5 gene is hypothesized to be a tumor-enhancing gene, however, studies regarding the involvement of the TXNDC5 in gastric cancer remain limited." (PMID 25663872, 2015). "In conclusion, the immunohistochemical expression of TXNDC5 may correlate with poor differentiation of the tumors and with a poor prognosis in gastric cancer patients." (PMID 25663872, 2015). "Inhibiting TXNDC5 expression in cervical cancer, castration-resistant prostate cancer, RCC, gastric cancer, laryngeal squamous cell carcinoma (LSCC), pancreatic cancer, and liver cancer can promote cell apoptosis and inhibit cell proliferation and migration." (PMID 35934705, 2022). "Thus, TXNDC5 may be a tumor-enhancing gene that is involved in gastric cancer." (PMID 25663872, 2015). "In addition, the expression of TXNDC5 was negatively correlated with the overall survival rate in RCC and gastric cancer." (PMID 35934705, 2022). "However, TXNDC5 overexpression does not significantly stimulate dendritic cell maturation, cytokine-induced killer cell development, or cytotoxicity, which are the major types of cells used in immunotherapy for gastric cancer." (PMID 38666927, 2024).
lung fibrosis (10 papers, 2020 to 2025). "The use of the inducible fibroblast-specific deletion of Txndc5 provides additional confirmation of the pathogenic role of fibroblastic TXNDC5 in the development and progression of lung fibrosis." (PMID 38666927, 2024). "Utilizing inducible fibroblast-specific deletion of Txndc5 further confirms the pathogenic requirement of fibroblastic TXNDC5 in the development and progression of lung fibrosis, thereby preventing and even reversing pulmonary dysfunction in BLM-treated animals." (PMID 36050716, 2022). "Inducing the fibroblast-specific deletion of thioredoxin domain containing 5, an ER resident chaperone, mitigates the progression of bleomycin-induced pulmonary fibrosis and lung function deterioration." (PMID 37627629, 2023). "Taken together, these results show that TXNDC5 modulates TGFβ signaling activity during the development of lung fibrosis and highlight the therapeutic potential to treat patients with PF by targeting TXNDC5 in lung fibroblasts." (PMID 36050716, 2022). "Here we show that an ER protein disulfide isomerase, thioredoxin domain containing 5 (TXNDC5), is highly upregulated in the lung tissues from both patients with idiopathic pulmonary fibrosis and a mouse model of bleomycin (BLM)-induced PF." (PMID 32848143, 2020). "Taken together, these results uncovered a previously unrecognized role of ER protein TXNDC5 in modulating TGFβ signaling activity and in the development of lung fibrosis." (PMID 32848143, 2020). "Here the authors show that a fibroblast-enriched endoplasmic reticulum protein, TXNDC5, promotes pulmonary fibrosis by stabilizing TGFBR1 and show the potential of TXNDC5 as a therapeutic target against pulmonary fibrosis." (PMID 32848143, 2020). "Herein, we revealed a critical yet previously undiscovered role of the lung fibroblast-enriched ER protein TXNDC5 in the pathogenesis of lung fibrosis." (PMID 32848143, 2020). "The results presented here demonstrate that depletion of Txndc5 in lung fibroblasts significantly lessened the progression of lung fibrosis induced by BLM and prevented lung function from deterioration." (PMID 32848143, 2020). "Taken together, these data showed that BLM treatment led to marked lung fibrosis and lung function impairment, whereas global deletion of Txndc5 protected against BLM-induced lung fibrosis and preserved lung function." (PMID 32848143, 2020). "To determine the in vivo functional role of TXNDC5, we used a mouse model of lung fibrosis induced by intra-tracheal instillation of bleomycin (BLM, 3 mg/kg)." (PMID 32848143, 2020). "Taken together, these results revealed a critical yet previously unrecognized role of TXNDC5 in the regulation of TGFβ signaling and in the pathogenesis of lung fibrosis." (PMID 32848143, 2020). "Consistent with the in vitro mechanistic experiments, global deletion of Txndc5 ameliorated BLM-induced lung fibrosis and respiratory dysfunction in mice." (PMID 32848143, 2020). "To determine the in vivo contribution of fibroblast TXNDC5 to pulmonary fibrosis, we generated a mouse line with inducible, fibroblast-specific Txndc5 deletion (Col1a2-Cre/ERT2*Txndc5fl/fl, abbreviated as Txndc5cKO)." (PMID 32848143, 2020). "In addition, TXNDC5 is involved in the progression of pulmonary fibrosis (PF) by modulating TGFβ signaling as well." (PMID 38666927, 2024). "In addition, it was found that inhibiting activity of IRE1α endoribonuclease can reduce the expression of TXNDC5 in activated fibroblasts and delay lung fibrosis induced by crystalline silica." (PMID 35934705, 2022). "Similarly, the role of TXNDC5 in renal and pulmonary fibrosis via the TGF-β pathway has been revealed by related studies." (PMID 35934705, 2022). "TXNDC5 promotes pulmonary fibrosis by augmenting TGFβ signalling through TGFBR1 stabilization." (PMID 36160018, 2022).
lung fibrosis (continued). "Using a mouse line with inducible, fibroblast-specific Txndc5 deletion, we have further demonstrated that inducing Txndc5 deletion in lung fibroblasts lessened the development and progression of lung fibrosis and lung function decline in mice with BLM-induced PF." (PMID 32848143, 2020). "MicroCT scanning showed that BLM treatment led to marked lung destruction, volume reduction, and extensive lung fibrosis in WT mice at 21 days, whereas knocking out Txndc5 preserved the lung structure and attenuated the volume reduction and fibrotic changes induced by BLM treatment." (PMID 32848143, 2020). "Our data also suggest that targeting TXNDC5 could be a powerful new therapeutic approach to mitigate lung fibrosis, thereby improving lung function and outcomes in patients with PF." (PMID 32848143, 2020). "Using a global Txndc5 knockout mouse line, we have shown that global deletion of Txndc5 could “prevent” the development of lung fibrosis induced by BLM." (PMID 32848143, 2020). "Collectively, increased expression of TXNDC5 transcript and protein in human IPF lungs and lung fibroblasts, as well as its strong positive correlation with multiple fibrogenic protein genes suggest the potential importance of TXNDC5 in the pathogenesis of lung fibrosis." (PMID 32848143, 2020). "The results presented here showed that TXNDC5 promotes lung fibrosis by enhancing TGFβ signaling activity via post-translational stabilization of TGFBR1 in lung fibroblasts, thereby leading to excessive lung fibroblast activation, proliferation, and ECM production." (PMID 32848143, 2020). "A pulmonary fibrosis study showed that a domain of PDI (TXNDC5) was highly upregulated in patients with idiopathic pulmonary fibrosis as well as a mouse model of this injury, suggesting that this protein could be a novel therapeutic target in the treatment of pulmonary fibrosis." (PMID 33381273, 2020). "Upregulated TXNDC5 can enhance TGFβ1 signaling by promoting the folding and stabilization of TGFBR1 in lung, leads to pulmonary fibrosis (PF)." (PMID 38629066, 2024). "In this study, the transcript and protein expression of TXNDC5 are upregulated in the lung tissues of human IPF patients and mice with BLM-induced lung fibrosis." (PMID 36050716, 2022). "Targeted deletion of Txndc5 protects against the development and progression of BLM-induced lung fibrosis." (PMID 32848143, 2020). "Because inflammatory response is a crucial mediator of lung fibrosis following BLM treatment, we went on to examine if global deletion of Txndc5 would impact pulmonary inflammation induced by BLM." (PMID 32848143, 2020). "In these experiments, Txndc5 deletion in lung fibroblasts was induced 7 days after BLM instillation, a time point when lung fibrosis was induced and began to expand, usually peaking at 2–3 weeks following BLM treatment in WT mice." (PMID 32848143, 2020). "Consistent with the induction of lung fibrosis by BLM, the transcript expression levels of various fibrogenic protein genes including Col1a1, Col3a1, Eln, Fn, Ctgf, as well as Txndc5, were significantly upregulated in BLM-treated mouse lungs (21 days post-BLM treatment)." (PMID 32848143, 2020). "Hydroxyproline content, a biochemical index for pulmonary fibrosis and collagen deposition, was markedly increased in WT, but not in Txndc5−/−, mouse lungs in response to BLM treatment." (PMID 32848143, 2020). "The notion that fibroblast-specific deletion of Txndc5 significantly lessened the development and progression of pulmonary fibrosis and lung dysfunction induced by BLM in mice, therefore, remains unchanged whether TXNDC5 contributes to EndoMT-mediated lung fibrogenesis or not." (PMID 32848143, 2020).
prostate carcinoma (10 papers, 2014 to 2026). A carcinoma that arises from epithelial cells of the prostate gland. "In Pca, TXNDC5 was significantly overexpressed in androgen-intrinsic prostate cancer and desmoplastic-resistant prostate cancer." (PMID 38629066, 2024). "In prostate cancer, TXNDC5 can directly interact with and stabilize the AR protein to promote Castration-resistant prostate cancer development and growth." (PMID 35296659, 2022). "TXNDC5 directly interacts with the androgen receptor protein to increase its stability and enhance its transcriptional activity, thus stimulating the growth of castration-resistant prostate cancer." (PMID 31570854, 2020). "Aberrant TXNDC5 expression has been reported in multiple malignancies, and is involved in the modulation of tumor cell cycle, proliferation, and migration, likely representing an important event in the progression of cervical cancer, prostate cancer, and lung cancer." (PMID 31331361, 2019).
cervical cancer (9 papers, 2017 to 2025). A primary or metastatic malignant neoplasm involving the cervix. "The present study suggests that TXNDC5 is a susceptibility gene in cervical cancer, and high expression of this gene contributes to abnormal angiogenesis, vasculogenic mimicry and metastasis by down-regulating SERPINF1 and TRAF1 expression." (PMID 29207620, 2017). "In this study, we detected a significant association between the rs408014 and rs7771314 SNPs at the TXNDC5 locus and cervical carcinoma using the Taqman genotyping method." (PMID 29207620, 2017). "In summary, the present study confirmed the significant association between the TXNDC5 gene and cervical carcinoma and demonstrated significantly increased TXNDC5 expression in the tumor tissues." (PMID 29207620, 2017). "In the present study, Taqman genotyping demonstrated a significant association between rs408014 and rs7771314 in the TXNDC5 locus and cervical carcinoma." (PMID 29207620, 2017). "In addition, our research group found that the TXNDC5 gene increases the risk of cervical cancer, oesophageal cancer and liver cancer." (PMID 35934705, 2022). "METTL3 maintained the mRNA stability of TXNDC5 to inhibit ER stress, further promoting cervical cancer cell metastasis." (PMID 39856747, 2025). "TXNDC5 can also contributes to abnormal angiogenesis in cervical cancer by regulating inflammatory factor receptor expression of SERPINF1 and TRAF1, which can activate the NF-κB signaling in inflammatory environments." (PMID 38629066, 2024). "TXNDC5 is upregulated in several cancer types, such as lung, liver, esophageal, stomach, breast, uterine, and cervical carcinoma." (PMID 39275334, 2024). "In vitro experiments have found that inhibiting the expression of TXNDC5 in cervical cancer cells leads to increased expression of SERPINF1 and TRAF1." (PMID 35934705, 2022). "In cancerous diseases, SERPINF1 functions as a tumor suppressor in cervical cancer, which is downregulated by TXNDC5, resulting in stimulating cell migration, vasculogenic mimicry and angiogenesis." (PMID 32595417, 2020). "We found that the inhibition of TXNDC5 expression significantly attenuated the capacity of this cervical cancer cell line to form tube-like structures in 3D culture conditions." (PMID 29207620, 2017). "Following normalization to GAPDH expression in the tissues, TXNDC5 expression was significantly increased in cervical cancer tissues compared with uterine myoma tissues (p = 0.0003)." (PMID 29207620, 2017). "TXNDC5 can promote angiogenesis, angiogenic mimicry and cell metastasis in cervical cancer." (PMID 38629066, 2024).